ACAT2 (acetyl-CoA acetyltransferase 2)
Diseases named in the same sentence as ACAT2 in open-access papers (continued):
Sharing a sentence is not in itself a finding about the gene and the disease.
melanoma (3 papers, 2021 to 2026). A malignant, usually aggressive tumor composed of atypical, neoplastic melanocytes. "This SOX10-TAF15 complex subsequently enhanced ACAT2 protein levels, stimulated cholesterol synthesis, suppressed apoptosis, and ultimately drove melanoma proliferation." (PMID 41694582, 2026). "In this study, we found that total cholesterol levels and the expression of acetyl-CoA acetyltransferase 2 (ACAT2), a key cholesterogenic enzyme, were significantly elevated in melanoma cells." (PMID 41694582, 2026). "Molecular targeting of ACAT2 or pharmacological inhibition of SOAT by avasimibe showed antiproliferative effects in melanoma cell lines and a synergistic drug interaction with PLX4032, an effect associated to increased ferroptosis." (PMID 35912092, 2022). "ACAT2-mediated de novo cholesterol synthesis promoted melanoma growth both in vitro and in vivo." (PMID 41694582, 2026). "The enhanced ACAT2 expression observed in lipid-starved resistant melanoma cells could be ascribed to mechanisms involving SREBF1/2 expression, which control upstream lipid metabolism pathways, and display upregulation in resistant cells." (PMID 35912092, 2022). "Furthermore, we identified that the transcription factor SOX10, which is critical for melanocyte development, was specifically highly expressed in melanoma and directly upregulated ACAT2 expression, thereby promoting cholesterol synthesis and tumor proliferation." (PMID 41694582, 2026). "Similarly, we show here that molecular silencing of ACAT2 impaired resistance to PLX4032, further supporting the evidence that interfering with cholesterol metabolism may impair melanoma cells BRAFi resistance." (PMID 35912092, 2022).
cholestasis (2 papers, 2022 to 2024). Impairment of the bile flow caused by obstruction within the liver, or outside the liver in the bile duct system. "PRR could reverse the abnormal changes of Cpt1a, Acat2, Ehhadh, and Hadha, among which Cpt1a, Ehhadh, and Hadha are fatty acid β-oxidation genes, indicating that fatty acid β-oxidation might play important role in the treatment of cholestasis by PRR." (PMID 36339580, 2022). "CSA, a well-known inducer of cholestasis, downregulated gene expression of CYP7A1, CYP27A1, BAAT, HNF4A, and INSIG1, while it upregulated ACAT2 and CCL20 gene expression." (PMID 38953992, 2024).
coronary artery atherosclerosis (2 papers, 2019 to 2021). "All these suggested that ACAT2-derived cholesteryl esters may promote arterial cholesterol accumulation during coronary artery atherosclerosis." (PMID 30696703, 2019). "ACAT2 is also responsible for incorporation of cholesteryl ester in apoprotein B-containing lipoproteins that leads to increased very low-density lipoprotein (VLDL) secretion and coronary artery atherosclerosis." (PMID 34490291, 2021).
dyslipidemia (2 papers, 2023 to 2025). "For instance, the Gram-positive bacteria binding receptor TLR2, which can also bind dietary fatty acids and plays a role in the progression of the metabolic syndrome, was upregulated in Acat2-overexpressing liver." (PMID 36378328, 2023). "In addition, the GLXB herb pair exerted therapeutic effects on dyslipidemia in ApoE-/- mice by increasing the level of butyric acid, a metabolite of the gut microbiota, decreasing the expression of NPC1L1, MTP, ACAT2, and ApoB48 proteins, and inhibiting the intestinal absorption of cholesterol." (PMID 41466480, 2025).
Hepatic steatosis (2 papers, 2014 to 2019). Steatosis is a term used to denote lipid accumulation within hepatocytes. "The direct role of ACAT2 linked to hepatic steatosis and glucose homeostasis was also proved in the mouse model." (PMID 31795276, 2019). "So the down-regulation of Acat2 in the current study might prevent dietary cholesterol-associated hepatic steatosis." (PMID 24505463, 2014).
hyperlipidemia (2 papers, 2016 to 2025). "Therefore, the ACAT2-specific inhibitors are effective in treating or preventing hyperlipidemia." (PMID 27536279, 2016). "Notably, metabolic DEGs such as ACSL1, ABCA1, ABCG1, ACAT2, ALOX5AP, PLA1A, and PPARG were elevated in hyperlipidemia." (PMID 39853712, 2025).
ovarian carcinoma (2 papers, 2020 to 2024). A malignant neoplasm originating from the surface ovarian epithelium. "Acetyl-CoA acetyltransferase 2 (ACAT2) is a lipid metabolism enzyme and rarely was researched in epithelial ovarian cancer (EOC)." (PMID 38178203, 2024). "Rare studies have reported the relationship between ACAT2 expression and chemo-resistance or ovarian cancer." (PMID 38178203, 2024). "Since ACAT exists predominantly in two isoforms (ACAT-1 and ACAT-2), it is essential to understand the expression levels of both isoforms in ovarian cancer cell lines." (PMID 31978092, 2020). "In comparison to ACAT-2, ACAT-1 expression varied significantly between ovarian cancer cell lines versus normal control cells." (PMID 31978092, 2020). "ACAT-2 expression was not altered during the transfection implicating ACAT-1 specific knockdown in all ovarian cancer cell lines." (PMID 31978092, 2020).
prostate adenocarcinoma (2 papers, 2024 to 2025). "Conversely, ACAT2 manifested low expression in stomach adenocarcinoma (STAD), head‐and‐neck squamous cell carcinoma (HNSC), prostate adenocarcinoma (PRAD), and liver hepatocellular carcinoma (LIHC)." (PMID 38213102, 2024).
steatosis (2 papers, 2020 to 2024). Increased lipid within the cytoplasm of cells. "Collectively, our previous study and current data indicate the development of severe steatosis was closely related to the genes involved in lipid synthesis, packaging, secretion, transportation, deposition or metabolism, including FADS, ELOVL1, ELOVL5, and ACAT2." (PMID 32054153, 2020).
viral infection (2 papers, 2022 to 2025). "Genes controlling the key steps in cholesterol biosynthesis, such as FDPS, ACAT2, MVD, LSS, and FDFT1, were transcriptionally commonly suppressed upon viral infection at 48 hpi." (PMID 40857262, 2025).
acute coronary syndrome (1 paper, 2019). Signs and symptoms related to acute ischemia of the myocardium secondary to coronary artery disease. "They found that ACAT2-derived CE in lipoproteins have strong potential value in the prediction of acute coronary syndrome." (PMID 30696703, 2019).
Anxiety (1 paper, 2023). Intense feelings of nervousness, tension, or panic often arise in response to interpersonal stresses. "Elevated ACAT2 expression was associated with less severe depression and anxiety sensitivity to publicly observable anxiety reactions, and GRN expression was inversely correlated with the severity of trait symptoms, including HA and neuroticism." (PMID 36750547, 2023). "ACAT2 expression was inversely correlated with the severity of depression and anxiety sensitivity to publicly observable anxiety reactions." (PMID 36750547, 2023). "Interestingly, ACAT2 expression was inversely correlated with the severity of depression and anxiety sensitivity to publicly observable anxiety reactions." (PMID 36750547, 2023).
aortic atherosclerosis (1 paper, 2019). A atherosclerosis that involves the aorta. "Further, ACAT-2–/– /ApoE–/– mice also had lower level of aortic atherosclerosis compared with controls." (PMID 30696703, 2019).
cholesterol metabolism disorder (1 paper, 2022). "Moreover, it could improve intestinal cholesterol metabolism disorder induced by high-fat and high-cholesterol diets via the reduction of the expression of HMGCR, NPC1L1, ACAT2, MTP, ASBT and IBABP mRNA or protein, increasing ABCG8 mRNA expression." (PMID 36816874, 2022).
colon cancer (1 paper, 2024). "ACAT2 can promote the development of colon cancer, but its efficacy in lung adenocarcinoma (LUAD) remains uncertain." (PMID 38213102, 2024). "A recent study shows that ACAT2 is overexpressed in tissues and cell lines of colon cancer (CRC)." (PMID 38213102, 2024).
COVID-19 (1 paper, 2024). A disease caused by infection with severe acute respiratory syndrome coronavirus 2. "Therefore, we explored the common pathogenesis of AMD and SARS-CoV-2, and found that COVID-19 and AMD have five common differences in FAMRG, namely FASD1, HMGCS1, ACOX2, ACAT2 and PECR." (PMID 38625951, 2024).
cystinosis (1 paper, 2021). Cystinosis is a metabolic disease characterized by an accumulation of cystine inside the lysosomes, causing damage in different organs and tissues, particularly in the kidneys and eyes. "Thus, on a broader perspective, this epigenetic mechanism could be associated with other IEMs, as for example: Sandhoff disease (OMIM #268800), ACAT2 deficiency (OMIM #203750), Mucolipidosis III gamma (OMIM #252605), cystinosis (OMIM #219800, 219750 and 219900) and galactosialidosis (OMIM #256540)." (PMID 34215320, 2021).
dyslipidaemia (1 paper, 2019). "Atorvastatin therapy attenuated dyslipidaemia, renal insufficiency, reduced hepatic lipids, HMG-CoA reductase and ACAT2 protein abundance and raised LDL receptor and lipase protein expression." (PMID 31828139, 2019).
esophageal adenocarcinoma (1 paper, 2025). A malignant tumor with glandular differentiation arising predominantly from Barrett mucosa in the lower third of the esophagus. "At the metabolic enzyme level, both acetyl-CoA acetyltransferase 2 (ACAT2) and the aldo–keto reductase AKR1C3 have been shown to confer radioresistance to ESCC and esophageal adenocarcinoma (EAC) by inhibiting ferroptosis." (PMID 41201667, 2025).
esophageal squamous cell carcinoma (1 paper, 2024). Esophageal squamous cell carcinoma (ESCC) is a type of esophageal carcinoma (EC) that can affect any part of the esophagus, but is usually located in the upper or middle third. "ACAT2 promotes radioresistance in oesophageal squamous cell carcinoma (ESCC) and high expression of ACAT2 is significantly correlated with lower overall survival." (PMID 38670954, 2024).
gallbladder polyps (1 paper, 2023). "However, acetyl coenzyme A acetyltransferase 2 (ACAT2) promotes both cytokinesis of cholesterol in the mucosa of gallbladder polyps and the binding of cholesteryl esters to lipoproteins." (PMID 36737734, 2023).
gallstones (1 paper, 2025). Solid crystalline precipitates in the biliary tract, usually formed in the gallbladder, resulting in the condition of cholelithiasis. "Isoform-specific differences in ACAT activity may provide an additional mechanistic explanation, with ACAT2 particularly implicated in gallstone formation, whereas altered ACAT1-driven macrophage esterification may contribute more prominently to cholesterolosis." (PMID 41010704, 2025).
hyperhomocysteinemia (1 paper, 2016). A serious metabolic condition caused by mutations in the MTHFR gene, medications, or nutritional deficiency. "Studies have detected a reduced ACat2 expression in hyperhomocysteinemia (HHcy) mice, suggesting that ACat2 might be related to the folate metabolic pathway through regulation on intracellular Hcy level." (PMID 27809850, 2016).
infertile (1 paper, 2013). "The gene ACAT2 is involved in cholesterol metabolism, and expression of ACAT2 in cumulus cells is increased for infertile women as compared to fertile women." (PMID 23759029, 2013).
liver cirrhosis (1 paper, 2022). "Decreased LCAT activity has been described in patients with liver cirrhosis, but whether ACAT2 activity is also low has not been clarified yet." (PMID 36551908, 2022).
liver disease (1 paper, 2023). "Another bile acid, glycocholic acid, which is reported to be dramatically increased upon liver injury and liver disease, was found to be decreased in our mice overexpressing Acat2 in the liver." (PMID 36378328, 2023).
lymph node metastasis (1 paper, 2024). "Furthermore, patients with higher ACAT2 expression had larger tumour sizes, a greater likelihood of lymph node metastasis and a more advanced pTNM stage." (PMID 38670954, 2024).
ocular melanoma (1 paper, 2019). A melanoma that arises from the structures of the eye or ocular adnexa. "Other tumor-related genes, such as ACAT2, PIR and CTBP1, were potentially regulated by m6A modifications in ocular melanoma." (PMID 31722709, 2019).
Parkinson disease (1 paper, 2024). A progressive degenerative disorder of the central nervous system characterized by loss of dopamine producing neurons in the substantia nigra and the presence of Lewy bodies in the substantia nigra and locus coeruleus. "A study about Parkinson’s disease revealed that member 9 of the 70 kDa Heat Shock Protein (HSPA9) might be a potential interactant of ACAT2 by tandem affinity purification/mass spectra." (PMID 38178203, 2024).
periodontitis (1 paper, 2025). An acute or chronic inflammatory process that affects the tissues that surround and support the teeth. "Machine learning models, combined with Gene Set Variation Analysis (GSVA), identified five key genes (RGS1, ACAT2, KDR, TUBB2A, TDO2) linked to periodontitis." (PMID 39935835, 2025).
renal carcinoma (1 paper, 2024). A carcinoma arising from the epithelium of the renal parenchyma or the renal pelvis. "The competitive binding of circRPL23A to miR-1233 directly targeted ACAT2 to restraining synthesis of cholesterol esters and inhibit the progression of renal carcinoma." (PMID 38341418, 2024).
Stroke (1 paper, 2016). Sudden impairment of blood flow to a part of the brain due to occlusion or rupture of an artery to the brain. "Grb2, Acot11, Acat2, Scp2, Anp32b and Ppp2r5d were down-regulated after stroke." (PMID 27699085, 2016).
cancer (22 papers, 2016 to 2025). A tumor composed of atypical neoplastic, often pleomorphic cells that invade other tissues. "Dysregulation of ACAT2 has been associated with various cancers." (PMID 41441336, 2025). "CancerSEA database at the single cell level was utilized to detect relations between ACAT2 expression and its correlation with the tumor functional status in different cancers." (PMID 38213102, 2024). "We detected in PR elevated levels of enzymes (COX-2, ACSS2, FDPS, FASN, ACAT2, ACLY, SLC12A2) and metabolites (arachidonic acid and carnitine) involved in lipid metabolism, which have been linked to radioresistance of cancer cells." (PMID 38410100, 2024). "In our research, we aim to examine the expression of ACAT2 in pan‐cancer and LUAD tissues, and to explore the prognostic significance of ACAT2 in LUAD patients." (PMID 38213102, 2024). "In our results, a pan‐cancer analysis found that ACAT2 was overexpressed in CHOL, BRCA, ESCA, BLCA, HNSC‐HPVpos, HNSC‐HPVneg, UCEC, KIRC, LUAD, KIRP, LUAD, THCA, and LUSC." (PMID 38213102, 2024). "While ACAT2 has limited value in cancers, ACAT1 has been found to be widely participated in tumor initiation and progression." (PMID 38720812, 2024). "ACAT2 mRNA levels were found to be significantly increased in carcinoma tissues (CA) (n = 414) when compared with those in paracarcinoma tissue (PA) (n = 210) in the GC cohort from The Cancer Genome Atlas (TCGA) database (p < 0.001)." (PMID 38670954, 2024). "ACAT-2 expression was observed in all ovarian cell lines however the difference in expression levels between cancer cells and normal control cells is relatively less when compared to ACAT-1." (PMID 31978092, 2020). "In recent years, fatty acid metabolism has been evaluated as a potential cancer target for treatment, and, according to the results, the inhibition of FASN and ACAT2 leads cancer cells to apoptosis." (PMID 31240215, 2019). "Across the different conditions and cells, the predicted selective and pH-specific targets GAPDH, GPI, and ACAT2 achieved the largest detrimental effect on cancer cell survival." (PMID 30065243, 2018). "ACAT2 is significantly upregulated, and promotes cancer cell growth and progression of CRC." (PMID 38213102, 2024). "Since the cytosolic ACAT2 enzyme is involved in cholesterol synthesis but the mitochondrial ACAT1 plays a more prominent role in cancer, it may be possible that cancer cells take advantage of ACAT2-mediated attenuated PDC activity rather than enhanced ACAT2 activity for cholesterol synthesis." (PMID 37958351, 2023). "The expression of 24 FAM-related pathway genes was more active in para-cancer tissues than that in LUAD tissues, such as ACAA1, ACAT2, and ADH1B." (PMID 37920207, 2023). "We performed immunohistochemical analysis of ACAT2, SPHK1, SNED1, KPNA2, BZW2 and KIF15 in cancer and normal tissues and statistically analyzed the staining intensity." (PMID 37202800, 2023). "REG3G, ACAT2, and ATF5 have also been found in various cancers." (PMID 31148949, 2019). "The top five genes were HMGCR, LDL1 (low‐density lipoprotein 1), ACAT2 (acetyl‐CoA acetyltransferase 2), NSDHL (NAD[P] dependent steroid dehydrogenase‐like), and LDLR1 (low‐density lipoprotein receptor 1), all of which were positively correlated with HMGCS1 in most cancer types." (PMID 34549901, 2022).